TMPRSS2 (transmembrane serine protease 2)
Diseases named in the same sentence as TMPRSS2 in open-access papers (continued):
Sharing a sentence is not in itself a finding about the gene and the disease.
cancer (continued). "On the contrary, we could not validate differences between control and cancer population for the TMPRSS2-ERG status." (PMID 26856686, 2016). "To evaluate the chronological development of TMPRSS2:ERG fusion and 6q15 deletions we searched for tumors with focal 6q15 deletions arising in homogeneously ERG-positive cancers and tumors with focal ERG positivity arising in homogeneously or heterogeneously 6q15 deleted cancers." (PMID 26684029, 2016). "SOX9 expression levels were comparable in luminal cells of normal prostate glands (50% SOX9 positive) and 3,671 cancers lacking TMPRSS2:ERG fusion (55% SOX9 positive), but was markedly increased in 3,116 ERG-fusion positive cancers (81% SOX9 positive, p<0.0001)." (PMID 26030748, 2015). "This could be seen in all cancers, in the subsets of TMPRSS2:ERG positive or negative, PTEN deleted or undeleted carcinomas (p < 0.0001 each)." (PMID 25894226, 2015). "However, genomic alterations in androgen signaling, the rearrangement of ETS transcription factors, especially the fusion of TMPRSS2-ERG, as well as the deletion of PTEN are known to be highly recurrent in primary cancers, early-onset cancers and castration-resistant prostate cancers." (PMID 24879454, 2014). "However, there is no clear data on the relationship of TMPRSS2 to other cancer types." (PMID 39350850, 2024). "They reported that TMPRSS2:ERG fusions occur in about 50 % of cancers and that they are unrelated to PSA recurrence in patients treated by radical prostatectomy while it is possible, that fusion positive cancers might react better to anti-androgen therapy than fusion negative tumors." (PMID 27530104, 2016). "Furthermore TMPRSS2:ERG is unique only to prostatic nonbenign cancers." (PMID 23957008, 2013). "Despite cancer patients often experience poorer outcomes following SARS-CoV-2 infection, the role of TMPRSS2 in different cancer types has not yet been analyzed in detail." (PMID 40055791, 2025). "In these cases, the N-terminal portion of TMPRSS2, including the cytosolic tail but not the catalytic domain, is commonly fused to the ERG transcription factor in cancer patients." (PMID 37896901, 2023). "Of all cancer forms analyzed, CCRCC and PRCC displayed the highest expression levels for ACE2 and NRP1 mRNA, whereas again TMPRSS2 expression was lower but not negligible." (PMID 36595529, 2023). "Next, we analyzed the expression values of ADAM17, HSPA5, TMPRSS2, FURIN, and ACE2 in different cancers and corresponding normal individuals." (PMID 35720350, 2022). "Strong ANO7 staining was less prevalent in cancers harboring TMPRSS2:ERG rearrangements (24%) and ERG expression (25%) than in cancer lacking ERG fusions (43%) or ERG expression (45%, P < 0.0001 each)." (PMID 33628598, 2021). "MAPT staining was seen in 15.2 and 16% of cancers with TMPRSS2:ERG fusion detected by immunohistochemistry and fluorescence in-situ hybridization, but in only 3.5 and 3.9% of cancers without ERG staining or ERG rearrangements." (PMID 30823906, 2019). "In primary PCa, this pathway was frequently activated, and separate analysis of TMPRSS2:ERG fusion gene-negative and -positive cancers revealed that the presence of this fusion protein was the most likely cause of Wnt pathway activity." (PMID 30733525, 2019). "In our comparison of the expression levels of target genes in fusion-positive with fusion-negative samples in each cancer type, we found four TFFGs (PML-RARA, RUNX1-RUNX1T1, TMPRSS2-ERG, and SFPQ-TFE3) that had 50 DETGs." (PMID 29299133, 2017). "TMPRSS2-ERG expression was detected in carcinoma foci, regions next to them, and in samples not adjacent to carcinoma foci." (PMID 26294063, 2015). "In addition, certain structural rearrangements were exclusively found in specific cancer types, as is the case for SLC45A3-BRAF and TMPRSS2-BRAF structural rearrangements in prostate tumors and no other cancer types." (PMID 39018217, 2024).
cancer (continued). "We were not able to validate TMPRSS2 fusions with CASZ1, SIM2, and C1orf61 due to the insufficient amount of RNA; however, all these genes are known to play roles in pathologic conditions, including cancers." (PMID 37300660, 2023). "In contrast, others have been shown to be most useful in determining which patients needs to be re-biopsied due to the initial biopsy being negative for cancer despite continued high clinical suspicion for occult cancer: PCA3, TMPRSS2-ERG, ExoDx Intelliscore, Select MDx, and ConfirmMDx." (PMID 36768533, 2023). "However, these two studies were focused towards the expression analysis of ACE2 and TMPRSS2 rather than CXCL10, which is an important inflammatory cytokine that plays an active role in cancer metastasis." (PMID 36239108, 2022). "The assays, including PCA3, TMPRSS2-ERG, ExoDx Intelliscore, Select MDx, and Confirm MDx, have potential for patients who need to be re-biopsied, where the initial biopsy was found to be negative for cancer." (PMID 31013716, 2019). "Interestingly, the four TFFGs (PML-RARA, RUNX1-RUNX1T1, TMPRSS2-ERG, and SFPQ-TFE3) with the highest MAII scores showed 50 differentially expressed target genes (DETGs) in fusion-positive versus fusion-negative cancer samples." (PMID 29299133, 2017). "While there was a large number of Bx Neg and No Bx patients with a detectable TMPRSS2:ERG fusion event in our current study, TMPRSS2:ERG expression level (analyzed via RQ) was highest in the Bx Pos group consistent with the confirmed presence of cancer." (PMID 27144529, 2016). "In general, the non-ETS aberrations can occur both in TMPRSS2-ERG negative and positive cancers." (PMID 23708091, 2013).
tumor (285 papers, 2006 to 2025). "Their findings indicated that high levels of TMPRSS2 were linked to increased infiltration of immune cells, such as lymphocytes and macrophages, in tumor tissues." (PMID 40145441, 2025). "In vitro and in vivo experiments confirmed that TMPRSS2 deficiency enhances tumor cell proliferation and invasion while modulating antitumor immunity." (PMID 40145441, 2025). "The study found that downregulation of TMPRSS2 was linked to increased proliferation, stemness, genomic instability, tumor progression, and worse survival in LUAD." (PMID 40145441, 2025). "This association suggests that TMPRSS2 plays a role in modulating the immune response within the tumor microenvironment." (PMID 40145441, 2025). "In vitro and in vivo experiments verified the association of TMPRSS2 deficiency with increased tumor cell proliferation and invasion and antitumor immunity in LUAD." (PMID 38862975, 2024). "Accordingly, tumor evolution analyses based on the genomic mutations detected in PCa patients support an early involvement of the TMPRSS2-ERG fusions in prostate tumorigenesis." (PMID 35267426, 2022). "The TIMER database was explored to evaluate the relationship between TMPRSS2 expression and tumor-associated fibroblast immune infiltration in different tumor tissues." (PMID 35281819, 2022). "The gene mutations of TMPRSS2 were explored in 32 common types of the tumour by the TCGA PanCancer Atlas database, mainly including mutation and copy number mutation." (PMID 34951103, 2022). "The findings illustrated that the expression of TMPRSS2 was closely related to the immune infiltration of tumor-associated fibroblasts in COPD, ESCA, HNSC, STAD, LIHC, and TGCT." (PMID 35281819, 2022). "In this research, the potential correlation between tumor-associated fibroblast immune infiltration in all TCGA tumors and TMPRSS2 was explored using the Timer 2.0 database." (PMID 35281819, 2022). "In UCEC and PRAD patients, the high expression of TMPRSS2 or low expression of IFITM3 in tumor tissues indicated a higher susceptibility to SARS-CoV-2 infection compared with the healthy individuals." (PMID 33061814, 2020). "Strong nuclear ELAC2 expression was associated with advanced tumor stage, nodal metastasis, higher Gleason grade, presence of TMPRSS2:ERG fusion, higher Ki67-labeling index and PTEN deletion." (PMID 31452838, 2019). "These include regulation of SOX9 expression by ERG, which is found in tumours with TMPRSS2:ERG fusions, and loss of Zbtb7a, which encodes a factor proposed to antagonize SOX9 function rather than expression." (PMID 29484136, 2018). "Proposed oncogenic mechanisms to achieve increased SOX9 include transcriptional activation by ERG, which is highly expressed in tumours with TMPRSS2:ERG fusions, and loss of Zbtb7a, encoding a protein that antagonizes SOX9 activity." (PMID 29484136, 2018). "We also review research into understanding how ETS fusions (in particular,TMPRSS2-ERG) andSPOP mutations contribute to tumor initiation." (PMID 30135717, 2018). "Remarkably, eQTL analysis stratified by fusion type demonstrated a positive correlation between SOX9 gene expression and the rs1859962 risk allele in TMPRSS2:ERG positive tumor tissue." (PMID 27798103, 2016). "The authors found a statistically significant association between TMPRSS2 gene rearrangement and the presence of advanced pathologic tumour stage (p = 0.04), defining advanced stage as pT2b." (PMID 27377958, 2016). "TMPRSS2:ERG score was positively associated with direct markers of tumor volume, including number of positive cores and maximum percentage of positive cores, in both the academic biopsy cohort and the community biopsy cohort." (PMID 26339615, 2015).
tumor (continued). "Deregulated expression of several ABC genes shows significant associations with advanced tumor stage, grade, other clinical variables, and TMPRSS2-ERG status." (PMID 26459268, 2015). "TMPRSS2-ERG was found to associate with these factors in a manner predicting a poor outcome of the patient (high tumor stromal expression of PDGFRβ, hyaluronan, von Willebrand factor and low stromal expression of Caveolin-1)." (PMID 24505269, 2014). "In multivariate Cox regression analysis including the established prognostic marker Gleason score and local tumor stage, presence of TMPRSS2-ERG in the tumor was significantly associated with poor prognosis and gave additional prognostic information." (PMID 24505269, 2014). "In terms of morphological features, blue-tinged mucin, a cribriform growth pattern, macronucleoli, intraductal tumor spread and signet-ring cell features are associated with the occurrence of the TMPRSS2-ERG fusion." (PMID 23708091, 2013). "Beyond the AR alterations in advanced tumors, three of the most common genetic alterations in PCa are: overexpression of Myc, loss of the tumor suppressor Pten, and fusion of Ets genes with upstream AR regulated promoter sequences (e.g., TMPRSS2-Erg)." (PMID 24199173, 2013). "BEX1 and FBLN were associated with ER, while FBLN1, HBEGF, KLK3, and TMPRSS2 were associated with tumor aggressiveness." (PMID 21134280, 2010). "The reduced expression of TMPRSS2 in SARS‐CoV‐infected cells hints at the potential susceptibility of tumor tissues in COVID‐19 patients with PCa to SARS‐CoV‐2 infection, which may worsen prognosis." (PMID 40145441, 2025). "Additionally, a high level of TMPRSS2 was associated with immune cell infiltration, indicating its potential role in tumor immunity and as a therapeutic target during the COVID‐19 pandemic." (PMID 40145441, 2025). "Dysregulation of TMPRSS2 expression and/or catalytic activity may cause both tumor formation and metastasis, contributing to the etiology of several cancer types, especially prostate cancer." (PMID 38555403, 2024). "Interestingly, TMPRSS2 is reportedly associated with tumor cell expression, different complex(es) formation, and pathways, as well as transcriptional mis-regulation in prostate cancer among COVID-19 and PASC patients." (PMID 38555403, 2024). "Furthermore, the genetic expression of ACE2, TMPRSS2, and Furin has been shown to be altered and implicated in the pathogenesis of several tumours, as previously shown." (PMID 37568724, 2023). "TMPRSS2 expression was reduced in different tumor stages and linked with lymph node metastasis." (PMID 35017320, 2022). "Experimental studies have shown that tumor somatic PTEN loss in combination with the TMPRSS2:ERG gene fusion may result in accelerated tumor progression." (PMID 29137428, 2017). "Expression levels of target genes could provide useful insights into how germline risk variants exert their effects, in particular in tumor subtypes according to TMPRSS2:ERG fusion status." (PMID 27798103, 2016). "This might indicate that the more aggressive phenotype that arises with the presence of TMPRSS2-ERG at least in part is caused by changes in the tumor stroma." (PMID 24505269, 2014). "Pten loss correlates with the TMPRSS2-Erg fusion in human tumor samples." (PMID 24199173, 2013). "Interestingly enough, the aggressive tumor behavior, i.e., metastatic disease, was associated with a copy number increase of TMPRSS2:ERG loci on chromosome 21." (PMID 24281166, 2010).
tumor (continued). "Also, we found that TMPRSS2 was positively related to AR and negatively associated with PD-1 and PD-L1 in LUAD tumor tissue (AA, AC), suggesting that TMPRSS2 agonists might be an immunomodulator of LUAD to anti-PD-1 based immunotherapy combination therapies." (PMID 36992839, 2023). "Transmembrane protease serine 2 (Tmprss2) is a 70-kDa serine protease family member that is associated with physiological and pathological processes such as digestion, tissue remodeling, blood coagulation, fertility, inflammatory responses, tumor cell invasion and apoptosis." (PMID 36316325, 2022). "Recent studies have shed light on how the expression of ACE2 and TMPRSS2 in tumor tissues influences the tumor microenvironment and impacts immune responses." (PMID 40145441, 2025). "Our study showed that TMPRSS2 affected the expression of the IFN signaling components including JAK-STAT genes in both tumor cell lines and patients’ samples, which is consistent with the COVID-19 genome databases (COVID19db; GEO: GSE147507)." (PMID 40055791, 2025). "Expression of another AR-driven gene, Tmprss2, was also decreased in these tumor areas with low ERG." (PMID 41321318, 2025). "The increased PD-L1 levels in TMPRSS2-transfected tumor cells were further supported by in silico data (COVID19db ID: COVID000010)." (PMID 40055791, 2025). "This study provides novel insights into the role of TMPRSS2 in various tumor systems and the impact of SARS-CoV-2 infection on the host immunogenicity via the activation of immune-relevant pathways." (PMID 40055791, 2025). "Androgen deprivation therapy (ADT) or AR antagonists can downregulate TMPRSS2 expression, potentially reducing both tumor growth and SARS‐CoV‐2 infectivity." (PMID 40145441, 2025). "These include deletion of the PTEN tumour-suppressor, TMPRSS2:ERG gene fusion, and other molecular subtypes that have become important biomarkers with significant effects on treatment and prognosis." (PMID 40165885, 2025). "For instance, androgen deprivation therapies (ADTs), which reduce androgen levels or prevent AR role, have been reported to reduce ERG expression in TMPRSS2:ERG fusion-positive tumours, thus reducing their oncogenic potential." (PMID 40165885, 2025). "C0 TMPRSS2+ Tumor EPCs were related to biological processes such as Vesicle organization, Macroautophagy, Endosome organization,etc." (PMID 38482016, 2024). "miR-145 functions as a tumor suppressor by regulating the cell cycle and apoptosis, and its underexpression is correlated with PCa progression and the presence of the TMPRSS2-ERG fusion protein." (PMID 39796656, 2024). "In HPV+ and HPV- groups, the proportion of C0 TMPRSS2+ Tumor EPCs subgroup in HPV+ group was the highest, and C3 PLP2+ Tumor EPCs subgroup in HPV- group was the highest." (PMID 38482016, 2024). "had detected the gene fusion of TMPRSS2-ERG in circulating tumor cells and urine sediments from PCa patients, respectively." (PMID 38800374, 2024). "TMPRSS2 downregulation correlated with increased proliferation, stemness, genomic instability, tumor progression, and worse survival in LUAD." (PMID 38862975, 2024). "Stable depletion of TMPRSS2 in H1975 cells reduced the ability to undergo anchorage‐independent growth in vitro and slowed tumor growth in vivo." (PMID 36975376, 2023).